BCL2L12 (BCL2 like 12)
Diseases named in the same sentence as BCL2L12 in open-access papers (continued):
Sharing a sentence is not in itself a finding about the gene and the disease.
allergic disease (3 papers, 2019 to 2021). An immune response that occurs following re-exposure to an innocuous antigen, and that requires the presence of existing antibodies against that antigen. "Similar to the pro-apoptotic of BCL2L12 in IL-1β-stimulated chondrocytes, BCL2L12 participated in the induction of aberrant Th2-biased inflammation in the intestinal mucosa and chronic rhinosinusitis with allergy." (PMID 34116684, 2021). "Previous reports show that CD4+ T cells from patients with allergic diseases express high levels of Bcl2L12 16, 17, the present data also show that sTh2 cells express high Bcl2L12 levels." (PMID 31929750, 2020). "The data show that sTh2 cells of subjects with allergic diseases show apoptosis resistance as well as high levels of Bcl2L12." (PMID 31929750, 2020). "Inhibition of Bcl2L12 restores apoptosis machinery in intestinal mast cells in FA mice, suggesting that inhibiting Bcl2L12 in mast cells has potential clinical application in the treatment of allergic diseases." (PMID 31410196, 2019). "Importantly, the second activation by administration of C48/80 did not induce mast cell activation-related FA response in MCd mice in contrast to WT mice, suggesting the therapeutic potential in the treatment of allergic diseases by inhibition of Bcl2L12 in mast cells." (PMID 31410196, 2019).
colorectal cancer (3 papers, 2020 to 2025). A primary or metastatic malignant neoplasm that affects the colon or rectum. "In this study, we used targeted nanopore sequencing to identify circular BCL2L12 transcripts in human colorectal cancer cells and investigated the effect of circRNA silencing on mRNA expression of the parental gene." (PMID 40106061, 2025). "In brief, nanopore sequencing following nested PCR amplification of cDNAs of BCL2L12 circRNAs from 7 colorectal cancer cell lines unraveled 46 BCL2L12 circRNAs, most of which described for the first time." (PMID 40106061, 2025).
gliosarcoma (3 papers, 2019 to 2025). A rare histological variant of glioblastoma (WHO grade IV) characterized by a biphasic tissue pattern with alternating areas displaying glial and mesenchymal differentiation (WHO). "This study laid the groundwork for a Phase 0 clinical trial (NCT03020017) which assessed the safety and efficacy of gold NP-based SNAs conjugated with siRNA specific to Bcl2L12 in patients with recurrent GBM or gliosarcoma." (PMID 40806198, 2025).
leukemia (3 papers, 2012 to 2022). A malignant (clonal) hematologic disorder, involving hematopoietic stem cells and characterized by the presence of primitive or atypical myeloid or lymphoid cells in the bone marrow and the blood. "Expression levels of BCL2 and BCL2L12 were altered during apoptosis induced by widely used chemotherapeutic drugs in human leukemia cells." (PMID 21941553, 2012). "BCL2L12 expression and stimulated proliferation and engrafting of leukaemia cells suggested CD82 and BCL2L12 as promising therapeutic targets in AML." (PMID 35057823, 2022).
ovarian carcinoma (3 papers, 2022 to 2025). A malignant neoplasm originating from the surface ovarian epithelium. "BUD31 overexpression drives an oncogenic splicing switch in BCL2L12 to produce full-length BCL2L12 that in turn confers cancer cells resistance to apoptosis promotes the proliferation of ovarian cancer cells." (PMID 36271053, 2022). "Taken together, these results suggest that ASO2 inhibits ovarian cancer cells proliferation by regulating BCL2L12 exon 3 skipping." (PMID 36271053, 2022). "More importantly, we verify that BUD31 drives an oncogenic splicing switch of BCL2L12, which in turn promotes ovarian cancer progression." (PMID 36271053, 2022). "BUD31 stimulates the inclusion of exon 3 to generate full-length BCL2L12 and promotes ovarian cancer progression." (PMID 36271053, 2022). "Next, we measured the protein level of BCL2L12 in ovarian cancer cells with BUD31 knockdown or overexpression." (PMID 36271053, 2022). "BCL2L12’s anti-apoptotic role is reported to impact ovarian cancer." (PMID 40261460, 2025). "To investigate whether the regulation of BCL2L12 splicing by BUD31 mediate the oncogenic role of BUD31 in ovarian cancer, we first analyzed TCGA data and found that BCL2L12 was positively correlated with BUD31." (PMID 36271053, 2022). "In addition, BUD31 was positively correlated with plenty of inclusion events, including BCL2L12 AS, in ovarian cancer based on PSI value profiles in the TCGA-Spliceseq database." (PMID 36271053, 2022). "More importantly, ovarian cancer patients with exon 3 inclusion in the TCGA-OV cohort showed poor overall survival, implying that inclusion of BCL2L12 exon 3 may be involved in ovarian cancer progression." (PMID 36271053, 2022). "Interestingly, the spliceosome inhibitors pladienolides B and isoginkgetin could also induce BCL2L12 exon 3 skipping and inhibit the proliferation of ovarian cancer cells." (PMID 36271053, 2022). "Here the authors show that splicing factor BUD31 enhances ovarian cancer progression by promoting exon inclusion in the anti-apoptotic BCL2 family member, BCL2L12." (PMID 36271053, 2022). "In the combined analysis of CLIP-seq, RIP-seq and RNA-seq data, we identified multiple potential direct binding targets (BCL2L12, RBCK1, E2F4, and CDK16) that may involve in BUD31-mediated ovarian cancer cell survival and proliferation." (PMID 36271053, 2022).
acute myeloid leukemia (2 papers, 2021). Acute myeloid leukemia (AML) is a group of neoplasms arising from precursor cells committed to the myeloid cell-line differentiation. "Thus, in this study we evaluated the expression of Lipocalin 2 (LCN) and BCL2L12, in newly diagnosed bone marrow samples taken from adult with Acute Myeloid Leukemia and to correlate their expression levels with clinical, laboratory data of the patients and prognosis and patient survival." (PMID 34319051, 2021).
allergic rhinitis (2 papers, 2019 to 2022). Inflammation of the nasal mucous membranes caused by an IgE-mediated response to external allergens. "Studies have shown that YPF can reduce the expression of Bcl2L12, promote the balance of T helper cells 1/2, and regulate immune function in patients with allergic rhinitis." (PMID 36619520, 2022). "Our previous studies found that Bcl2L12 was involved in immune deregulation by interfering with the expression of IL-10 in peripheral B cells of patients with allergic rhinitis 16 or inflammatory bowel disease 32 and facilitating the development of Th2 polarization." (PMID 31410196, 2019).
eosinophilia (2 papers, 2023 to 2025). "Elevated Bcl2L12 levels likely exacerbate eosinophilic infiltration into nasal mucosal tissues by augmenting Th2 cell differentiation and cytokine production, thereby intensifying type 2 inflammation and eosinophilia within nasal mucosal tissues and heightening the risk of CRSwNP recurrence." (PMID 40617234, 2025).
nasopharyngeal carcinoma (2 papers, 2023 to 2025). A carcinoma arising from the nasopharyngeal epithelium. "Previous study found that Bcl2L12 was a novel biomarker for the prediction of short-term relapse in nasopharyngeal carcinoma." (PMID 40617234, 2025). "High expression of BCL2L12 was related to unfavorable prognosis in nasopharyngeal carcinoma and might suggest a novel biomarker for predicting short-term relapse." (PMID 37077419, 2023).
alcoholism (1 paper, 2022). "The downstream function of BCL2L12 is enriched in systemic lupus erythematosus, alcoholism, and other diseases." (PMID 35602301, 2022).
chronic lymphocytic leukemia (1 paper, 2023). "The products of BCL2 and its homologs, including BAX and BCL2L12, are implicated in chronic lymphocytic leukemia (CLL)." (PMID 37424436, 2023). "Our data suggest a multifaceted role of BAX and BCL2L12 circRNAs in B‐cell CLL." (PMID 37424436, 2023).
Cirrhosis (1 paper, 2016). A chronic disorder of the liver in which liver tissue becomes scarred and is partially replaced by regenerative nodules and fibrotic tissue resulting in loss of liver function. "Most notably, up-regulation of caspase-9 and epithelial membrane protein 1 (EMP1) was associated with fibrosis and Bcl-2-related proline-rich protein (BCL2L12) and programmed cell death protein 1 precursor (PDCD1) was associated with cirrhosis." (PMID 27280444, 2016).
laryngeal tumors (1 paper, 2012). "For instance, BCL2L12, a member of the BCL2 family of apoptosis-related genes, is overexpressed in undifferentiated nasopharyngeal carcinoma and in poorly differentiated TSCC, whereas its mRNA levels are lower in LSCC of advanced TNM stage, compared to early-stage laryngeal tumors." (PMID 23083099, 2012).
lung carcinoma (1 paper, 2025).
Lymphadenopathy (1 paper, 2021). Enlargement (swelling) of a lymph node. "Comparison revealed no statistical significant relation between high and low BCL2L12 gene expression in AML patients regarding demographic and clinical data: age (P value:0.45), hepatomegaly (P value: 0.66) and splenomegaly (P value: 0.73) and lymphadenopathy (P value: 0.65)." (PMID 34319051, 2021).
nasal polyps (1 paper, 2025). "Bcl2L12 plays an important role in the inflammatory response, but its role in chronic rhinitis with nasal polyps (CRSwNP) is unknown." (PMID 40617234, 2025).
Splenomegaly (1 paper, 2021). Abnormal increased size of the spleen. "Additionally, statistical significant relationships were found between BCL2L12 expression level and CD117 expression, the presence of splenomegaly and chemotherapy response." (PMID 34319051, 2021).
tumor (29 papers, 2012 to 2025). "Once inside the tumor, NU-0129 targets the Bcl2L12 gene,which has been associated with tumor growth and prevents programmedcell death (apoptosis)." (PMID 40787345, 2025). "NU-0129 exhibited prominent tumor accumulation (ranging between 4 × 109 and 1.1 × 1011 particles/g of tumor tissue), with 20% of intratumoral SNA being located inside tumor cells, which induced a reduction of tumor-associated Bcl2L12 protein expression." (PMID 36045273, 2023). "The Bcl2L12 gene expressed in glioblastoma multiforme is associated with tumor growth and its expression blocks apoptosis in tumor cells promoting tumor growth." (PMID 36012138, 2022). "The clinical study demonstrated that NU-0129 uptake into glioma cells correlated with significant underexpression of tumor-associated Bcl2L12 protein, as shown by comparison of NU-0129-treated recurrent vs. matched primary untreated tumor." (PMID 36012138, 2022). "As a result, gold enrichment was observed in tumor-associated endothelium, macrophages, and tumor cells, and the expression of tumor-associated Bcl2L12 protein was reduced." (PMID 35874843, 2022). "Although the full-length mRNA transcript of Bcl2L12 is expressed in many tissues, its overexpression in most human glioblastomas has been associated with tumor cell progression and tumor cell resistance to apoptosis." (PMID 34863235, 2021). "The uptake of NU-0129 into glioma cells was correlated with a reduction in tumor-associated Bcl2L12 protein expression." (PMID 34924904, 2021). "In this study, patients with recurrent GBM were treated with intravenous administration of siBcl2L12-SNAs revealing remarkable gold enrichment in the tumor-associated endothelium, macrophages, and tumor cells, as well as reduction in tumor-associated Bcl2L12 protein expression [83••]." (PMID 37071295, 2023). "Designed to cross the BBB, NU-0129 delivers nucleic acids targeting the Bcl2L12 gene, which promotes tumor growth by preventing apoptosis." (PMID 40565099, 2025). "To examine the role of BCL2L12 in EYA1's tumor-promoting effects, we overexpressed BCL2L12 in EYA1-knockdown cells." (PMID 39897043, 2025). "Overexpression of BCL2L12-T33A significantly enhanced tumor formation, as indicated by increased tumor volume and weight, whereas cells overexpressing BCL2L12-T33E showed a weaker tumor formation ability, although still greater than that of the control group." (PMID 39897043, 2025). "Consistently, MBG3 and NB tumours of the INFORM cohort expressed BCL2L12 at comparatively low levels and BBC3 at above-average levels." (PMID 38942989, 2024). "Nevertheless, future clinical studies (phase II and III) will be necessary to assess the therapeutic efficacy of these nanoconstructs beyond the reported Bcl2L12 downregulation and AuNP tumor accumulation." (PMID 36045273, 2023). "PRMT1 and BCL2L12, the top two upregulated regulators of S‐CC, also play critical roles in tumor development." (PMID 36637997, 2023). "HAT1 also functions as a transcription factor to regulate the tumor microenvironment, sensitivity to immunotherapy, and the expression of various genes, such as BCL2L12 and FAS." (PMID 37513949, 2023). "Intravenous administration of gold SNAs conjugating with Bcl2L12-targeting siRNAs reduced Bcl2L12 mRNA levels, increased apoptosis, and decreased tumor burden in a mouse orthotopic xenograft model." (PMID 33807183, 2021). "This oncogene BCL2L12 allows tumor cells to escape apoptosis, thus promoting tumor survival and growth." (PMID 34924904, 2021).
tumor (continued). "In contrast, Bcl2L12 exhibited low or undetectable levels in cells of glial origin in normal brain surrounding tumor tissue or in low-grade astrocytoma." (PMID 22431925, 2012). "Thus, siRNA can target and block the expression of Bcl2L12, disturbing the growth and propagation of tumor cells." (PMID 36045273, 2023). "In addition, silencing BUD31 also decreased BCL2L12 expression in the xenograft tumor in vivo." (PMID 36271053, 2022). "Comparing the four canonical MB subgroups in detail, Group 3 tumours both expressed BCL2L1 (BCL-XL) and BBC3 at significantly higher levels than the other subgroups and showed significantly lower BCL2L12 expression than the MBSHH and MBWNT subgroups." (PMID 38942989, 2024). "As mere expression of the anti-apoptotic target proteins has not been clearly demonstrated to predict response to BH3-mimetic treatment, we investigated the expression of the recently suggested predictive biomarkers BCL2L12 and BBC3 for paediatric tumours." (PMID 38942989, 2024). "Furthermore, the combination drug decreased the mRNA expression levels of downstream c-Myc targets, including CDK4, PABPC1, ATF4, BCL2L12, and HMGA 31, in MDA-MB-231 and BT-549 cells, which are important effectors of c-Myc inhibition-induced tumor suppression." (PMID 41281757, 2025). "More recently, comprehensive oncogenomic and tissue microarray analyses validated robust amplification (nonfocal gain of chromosome 19q13) and overexpression of the noncanonical Bcl-2 family protein, Bcl-2-Like 12 (Bcl2L12) in primary GBM tumor specimens." (PMID 22431925, 2012).
cancer (14 papers, 2013 to 2025). A tumor composed of atypical neoplastic, often pleomorphic cells that invade other tissues. "The discovery of the non-coding nature of the BCL2L12 mutations made us suspect that other identified clusters of synonymous and/or missense mutations also could be wrongly annotated in cancer genomics databases." (PMID 40359938, 2025). "Our findings thus suggest that ASO-mediated BCL2L12 exon 3 skipping is a promising strategy for cancer therapy." (PMID 36271053, 2022). "The prognostic significance of BCL2L12 mRNA expression has already been assessed in several cancer types." (PMID 36606241, 2022). "Early reports indicated that Bcl2L12 played a role in the anti-apoptotic feature of glioma cells, as wells as some other cancers." (PMID 31410196, 2019). "Importantly, pan-cancer analysis of the TCGA data showed that BCL2L12 expression level and the proportion of BCL2L12-L were higher in most types of tumors than in corresponding normal tissues." (PMID 36271053, 2022). "Because Bcl2L12 plays a role in inducing an anti-apoptotic feature in cancer cells 13, we sought to determine whether Bcl2L12 was also involved in inducing apoptotic defects in mast cells." (PMID 31410196, 2019). "Early studies found that Bcl2L12 was mainly involved in the pathogenesis of cancers." (PMID 31410196, 2019). "Increasing the expression of antiapoptotic regulator Bcl2l12 in cancer can achieve similar end." (PMID 23382867, 2013). "Three of these have been directly linked to apoptosis: miR-4767 in vascular epithelial cells through targeting BCL2L12 and EGFR, miR-3202 which was shown to cause apoptosis in endothelial cells, and miR-384 has been linked to inducing apoptosis in certain types of cancers." (PMID 35468884, 2022). "When running CBaSe on our pan-cancer dataset, five out of nine genes detected as significant by CBaSe were also detected as significant by SSB-dN/dS (BCL2L12, TERT, AP2S1, KRI1, TMEM214)." (PMID 29855388, 2018). "Gain of 19q would result in increased copy number of several well known genes with involvement in cancer, such as BAX, CEACAM1, AKT2 and BCL2L12." (PMID 24144331, 2013). "Therefore, it would be interesting to investigate whether BCL2L12 circRNAs identified in cancer cells are also present in non-cancerous colorectal cell lines." (PMID 40106061, 2025).
cardiovascular diseases (1 paper, 2024). "In cardiovascular diseases, Bcl2L12 forms a complex with c-Myc in eosinophils (Eos) to inhibit FasL expression and confer apoptosis resistance of Eos in myocardial tissue." (PMID 39578852, 2024).
infection (1 paper, 2017). The state of being infected such as from the introduction of a foreign agent such as serum, vaccine, antigenic substance or organism. "Finally, several pro-apoptotic genes, including Bcl3, Bcl10, Malt1 and Dedd2, were up-regulated in response to muriform cells infection whereas Bcl2l12, coding to anti-apoptotic factor, was down-regulated, suggesting that infection of macrophages with muriform cells could induce apoptosis." (PMID 28355277, 2017).
BCL2L12 also shares sentences with these, for which no sentence is quoted: inflammatory bowel disease (2 papers); Allergy (1); autoimmune thyroid disease (1); basal cell carcinoma (1); chronic rhinosinusitis (1); colon adenocarcinoma (1); epithelioid sarcoma (1); fibrosis (1); food allergy (1); hypothyroidism (1); inflammation (1); laryngeal squamous cell carcinoma (1); malignant glioma (1); multiple sclerosis (1); nodular melanoma (1); osteoarthritis (1); ovarian tumor (1); rheumatoid arthritis (1); skin cancer (1); superficial spreading melanoma (1); systemic lupus erythematosus (1); undifferentiated nasopharyngeal carcinoma (1); vitiligo (1).